APC (APC regulator of Wnt signaling pathway)
Diseases named in the same sentence as APC in open-access papers (continued):
Sharing a sentence is not in itself a finding about the gene and the disease.
hepatocellular carcinoma (44 papers, 2002 to 2026). A malignant tumor that arises from hepatocytes. "FAP is caused by germline mutations in the adenomatous polyposis coli (APC) gene that results in the triggering of upper and lower gastrointestinal polyps and carcinomas, hepatocellular carcinoma and hepatoblastoma (less frequently)." (PMID 34449596, 2021). "Only colorectal cancer predominantly harbours mutations in APC, whereas other cancer types (hepatocellular carcinoma, solid pseudopapillary tumours of the pancreas) have activating mutations in β-catenin (CTNNB1)." (PMID 26240067, 2015). "Not surprisingly, among them, CDC20, CCNA2, and BUB1 are all associated with APC-related processes, which may be key nodes in the prognosis and occurrence of hepatocellular carcinoma." (PMID 36479313, 2022). "Such mutations also occur in other cancers, including hepatoblastomas and hepatocellular carcinomas (HCC), and APC and β-catenin mutations have been found together in the same tumor." (PMID 39766864, 2024). "To date, in the literature, there were practically no scientific reports utilizing a similar approach, except for a study demonstrating that CpG methylation solely on the sense DNA strand of the APC gene was specific to hepatocellular carcinoma." (PMID 39456618, 2024). "Regarding the role played by gene mutations, changes in Hbx modulate the expression of Wnt-5a in hepatoma cells, whereas inactivating mutations in APC, AXIN1 and AXIN2 genes or methylation in APC aberrantly modify the Wnt signaling response." (PMID 37512809, 2023). "Hypermethylation of the promoter of the tumor suppressor gene, adenomatous polyposis coli (APC), occurs in various malignancies, including hepatocellular carcinoma (HCC)." (PMID 22073196, 2011). "In cancer, constitutive Wnt signaling can be achieved, for example, by loss‐of‐function mutations in the components of the degradation complex adenomatous polyposis coli (APC) and Axin1, which are major tumor suppressors in colorectal and hepatocellular cancer, respectively." (PMID 38135904, 2024). "According to cBioPortal database, APC is the top 1 mutated tumor suppressor gene in colon adenocarcinoma (COAD, 68.6% mutation rate) and CTNNB1 (30.6% mutation rate) is the most frequently mutated proto-oncogene in hepatocellular carcinoma (HCC)." (PMID 36703130, 2023). "Mutations in the adenomatous polyposis coli (APC) gene have not been observed in experimental or human hepatoma." (PMID 24396396, 2014). "However, this oncogenic monopoly is not universal; CTNNB1 mutations often replace APC loss in hepatocellular carcinoma (HCC) and medulloblastoma, highlighting the context-dependent nature of WNT perturbation." (PMID 40874062, 2025). "This study was performed to determine the clinical significance of adenomatous polyposis coli (APC)-binding protein end-binding 1 (EB1) in hepatocellular carcinoma (HCC) and to characterize its biochemical role in comparison with previous reports." (PMID 32956413, 2020). "Prior work in hepatocellular carcinoma (HCC) demonstrated that CCT4 physically interacts with Cdc20, a key activator of APC/C, and this interaction promotes the disassembly of the mitotic checkpoint complex (MCC) to activate APC/C." (PMID 41403933, 2025). "The present study aimed to quantitatively determine the aberrant methylation signal of the adenomatous polyposis coli (APC) gene in hepatocellular carcinoma (HCC), and to evaluate whether hypermethylation of the APC promoter could be a prognostic biomarker for HCC." (PMID 24765201, 2014). "Similarly, miR-146a suppression as often seen in hepatocellular carcinoma (HCC), leads to increased VEGF expression through downregulation of APC and upregulation of HAb18G, thereby portending a poor prognosis." (PMID 27231010, 2016).
hepatocellular carcinoma (continued). "For several loci the frequency of aberrant hypermethylation is indistinguishable from conventional hepatocellular carcinoma arising in the non-cirrhotic liver, whereas for the APC and the CDH1 gene statistically significant differences in hypermethylation could be found." (PMID 21060828, 2010).
colon adenoma (43 papers, 1997 to 2025). An adenoma that arises from the colon. "APC, a tumor suppressor gene that is mutated in >80% sporadic colon adenoma and cancers, regulates the expression of a set of genes that control cell growth and tumorigenesis." (PMID 39413959, 2024). "Here, we report a case of sporadic multiple colonic adenomas that were accompanied by an APC-truncating mutation." (PMID 36826061, 2023). "The increased co-expression of KITENIN and ErbB4-CYT-2 promotes the transition from colonic adenoma to adenocarcinoma in the tumor microenvironment associated with APC loss." (PMID 34935584, 2021). "APC, associated with the dysregulation of the Wnt signaling pathway, was recognized as the early driver gene mutated in both colon adenomas and carcinomas." (PMID 34163531, 2021). "The increased co-expression of ErbB4-CYT-2 with KITENIN promoted the transition of colon adenoma to adenocarcinoma in tumor microenvironment of APC loss." (PMID 32117908, 2020). "First, APC or CTNNB1 mutations in LGR5+ colon stem cells give rise to human colon adenomas by constitutively activating WNT signaling to sustain the intestinal SC program and bypass cellular differentiation." (PMID 26744320, 2016). "While it is known that APC or CTNNB1 mutation activates aberrant WNT signaling to give rise to colon adenomas, the programs that promote their transformation to carcinomas are not well characterized." (PMID 26744320, 2016). "Mutations inactivating the APC tumor suppressor gene are believed to be critical initiating lesions in the majority of colon adenomas and carcinomas." (PMID 26528816, 2015). "Certain mutations in the colon adenoma-to-carcinoma pathway, such as mutations to the APC gene and activation of the Src gene, have also been described in BE." (PMID 25085954, 2014). "However, an in vivo study published in Science showed that LEF1 restricts ectopic crypt formation and tumor cell growth in colon adenomas from APC-deficient mice." (PMID 39200196, 2024). "KRAS mutations are frequently found after APC inactivation in large colonic adenomas." (PMID 33135632, 2020). "Patients with more than 100 colonic adenomas should be tested for an APC gene mutation." (PMID 26586118, 2015). "Most sporadic colon adenomas and carcinomas also harbour APC gene mutations." (PMID 15982419, 2005). "APC mutations are hypothesized to be the initial events in sporadic colon adenomas." (PMID 39339648, 2024). "STRAP has been shown to be upregulated in more than 50% of colon adenomas, and the inactivation of APC or the activation of Wnt/ß-Catenin signaling increases the expression of STRAP." (PMID 40558481, 2025). "It is increased in colon adenomas and negatively regulates the expression of the adenomatous polyposis coli (APC) gene." (PMID 31717435, 2019). "In summary, we report widespread genetic heterogeneity within colon adenomas and show that this heterogeneity affects genes and pathways functionally associated with the development of CRC, such as APC, KRAS and the MMR." (PMID 30166531, 2018). "While changes in cfDNA or mutations were not detectable, NGS analysis unmasked extensive genetic heterogeneity of colonic adenomas, affecting known drivers such as APC, KRAS and MMR genes." (PMID 30166531, 2018). "Other models were based on APC gene deletion: the deletion of both copies of the APC gene induced colon adenoma formation." (PMID 29652830, 2018). "Among these mutated genes, mutations in APC, FBXW7, KIAA1409, COL4A6, FAM181A, TFR2 and NRXN3 were previously reported in colon adenomas or adenocarcinomas." (PMID 23301059, 2013). "In sporadic colonic adenomas, the initiating event seems to be loss of heterozygosity (LOH) at the APC gene, followed by a second hit in the APC gene." (PMID 19332896, 2009).
colon adenoma (continued). "Additionally, APC methylation has been detected in colon adenoma, further evidence that it is an early event." (PMID 26884349, 2016). "Patients carrying germline APC mutations develop multiple colonic adenomas at younger age and higher frequency than non-carrier cases which indicates that silencing of one APC allele may be sufficient to initiate the transformation process." (PMID 15982419, 2005).
melanoma (42 papers, 2007 to 2026). A malignant, usually aggressive tumor composed of atypical, neoplastic melanocytes. "APC variants are considered to contribute to esophageal cancer and melanoma and are known to have prognostic and therapeutic implications as well." (PMID 37277882, 2023). "Other cancers display a lower number of APC mutations, whereas endometrial carcinoma, esophagogastric adenocarcinoma, and melanoma exhibit over 10% APC mutations." (PMID 35359365, 2022). "Inactivating mutations and hypermethylation of APC have been found responsible for reduced expression in melanoma cell lines and tissue." (PMID 34639015, 2021). "Several later studies have shown much lower frequencies of mutations in CTNNB1 and APC, which put into question the importance of a genetic component in aberrant activity of β-catenin in melanoma." (PMID 32659938, 2020). "In melanoma, frequencies of mutations in APC, AXIN1 and CTNNB1 are low, reaching according to cbioportal.org 10%, 2.9% and 5.9%, respectively, however, a significant interstudy variability exists." (PMID 32659938, 2020). "Abnormal activation of Wnt/β-catenin signaling, due to loss-of-function mutations in APC or activating mutations in β-catenin has been linked to tumorigenesis in many settings including melanoma, breast, colon and hepatocellular carcinomas." (PMID 26029888, 2015). "APC loss of function may contribute to the upregulation of the Wnt/β-catenin signaling pathway, favoring melanoma progression." (PMID 36230787, 2022). "For instance, activating mutations in APC or β-catenin are relatively rare in melanoma cells." (PMID 24281103, 2010). "De-regulation of WNT signaling is a well-established hallmark of certain types of human cancer, such as CRC and melanoma, in which a high percentage of mutations in the β-catenin destruction complex components APC and AXIN or in β-catenin itself have been described." (PMID 17897439, 2007). "In another study, while a CTNNB1 missense mutation and a truncating APC mutation were reported only in one out of forty cell lines, it has been demonstrated that hypermethylation of APC promoter was present in about 15% of melanoma biopsies and cell lines suggesting transcriptional silencing." (PMID 32659938, 2020). "In vitro experiments evidenced that the suppression of APC transcripts of melanoma cells (hairpin RNAs) led to a Wnt signaling increase in cell proliferation, thus stabilizing levels of β-Catenin." (PMID 35621644, 2022). "To shed some light into a potential significant biological relevance of NSD1 in the pathogenesis of melanoma, we focused on co-expressed genes, highlighting the tumor suppressor APC as one of the top NSD1 co-expressed genes (cBioPortal.org)." (PMID 36230787, 2022). "Among AJ, renal cancer (for either sex) and melanoma (in males only) were noted at a higher prevalence among APC I1307K carriers compared with healthy individuals [OR 1.64 (95% CI 1.04–2.47) and OR 2.04 (95% CI 1.24–3.22); p < 0.05, respectively]." (PMID 36497357, 2022). "By analogy with Sotos syndrome, we propose that in malignant melanomas, APC operates downstream NSD1." (PMID 36230787, 2022). "In particular, inhibition of APC transcripts in melanoma cells was insufficient to increase the levels of Wnt signaling, but still led to significant increases in cell proliferation rate." (PMID 34639015, 2021). "This shows that the tumor suppressor function of melanocyte APC is dose dependent: silencing of APC can contribute to melanoma development when the expression is reduced to a level that increases cell proliferation, but does not decrease the invasiveness." (PMID 34639015, 2021). "Nonetheless, β-catenin, APC and AXIN2 mutations are rare in primary melanoma specimens, in comparison to well-characterized melanoma cell lines cultured in vitro for a long period." (PMID 33212834, 2020).
melanoma (continued). "Genes where a statistically significant difference in mutation rate was observed were APC (p = 9 × 10−7) in CRC, STK11 (p = 0.008) in NSCLC, and CDKN2A (p = 0.02), ERBB4 (p = 9 × 10−4), FLT3 (p = 0.02), and KDR (p = 0.01) in melanoma." (PMID 28196074, 2017). "Point mutations or gene fusions in other genes (e.g., mutations in BRAF, KRAS, APC, and MET genes, or gene fusions in ZEB2‐ALK and SOX5‐RAF1 genes) may be associated with melanoma proliferation or melanoma progression in satellite nevi or LCMN." (PMID 41474606, 2026). "Of note, most co-occurring mutations in melanoma BRAF Class 2 and 3 (KMT2A, NOTCH1, APC) are of unknown significance, whereas those in Class 1 are amplifications and putative drivers such as NOTCH2 and MET amplifications." (PMID 38275886, 2024). "Among NAW, the APC I1307K rate was higher among melanoma patients in both sexes [OR 2.54 (95% CI 1.57–3.98), p < 0.01], as well as in breast (female only) and prostate (male only) cancer patients [OR 1.73 (95% CI 1.18–2.65), p < 0.01; OR 2.42 (95% CI 1.45–3.94), p < 0.01, respectively]." (PMID 36497357, 2022). "When NSD1′s activity is altered, the H3K36 active mark will not accumulate on APC’s promoter region; therefore the expression of the tumor suppressor APC remains repressed, subsequently the Wnt/β-catenin pathway will be constantly active, which would favor melanoma progression." (PMID 36230787, 2022). "In this cohort, the patient harboring the APC gene VUS at c.1564 A > G had a significant family history of esophageal cancer, melanoma and thyroid cancer in first degree relatives." (PMID 37277882, 2023). "Studies disclosed that methylation of genes like APC, PYCARD, and COL11A1 is relevant to the incidence of melanoma, and histone H3K27me3 upregulation can promote melanoma progression." (PMID 36060650, 2022). "Lastly, SKMEL28 is the only line in our panel with a mutation in APC, a tumor suppressor that antagonizes WNT signaling and has been shown to be nonfunctional in patients with melanoma." (PMID 26405815, 2015). "Although mutations of the β-catenin gene and APC have already been detected, the WNT signaling pathway has not been extensively implicated in melanoma development this far, due to the fact that defective β-catenin is rarely identified although it clearly acts as a melanoma-specific antigen." (PMID 22007305, 2011).
rectal cancer (38 papers, 2011 to 2025). A primary or metastatic malignant neoplasm that affects the rectum. "In this study, we describe a case of an index patient with FAP and rectal cancer harboring germline mutations in both APC and BRCA2, as well as somatic ERBB2 mutations." (PMID 39985003, 2025). "Secondary rectal cancer tumors had distinct molecular features, including lower mutational burden, lower frequency of APC alterations, higher rates of SMAD4 inactivation, and increased rates of frameshift and inframe deletions." (PMID 40100215, 2025). "In conclusion, we present a rare case of a de novo FAP patient with rectal cancer, characterized by double germline mutations in APC and BRCA2, alongside somatic ERBB2 mutations." (PMID 39985003, 2025). "The second patient with the variant in the APC gene, aged 41, also had over 1000 adenomatous polyps ranging from 0.1 and 0.4 cm and rectal cancer pT1N0M0 and underwent restorative proctocolectomy." (PMID 41170447, 2025). "For example, mutations that result in the loss or inactivation of the adenomatous polyposis coli (APC) gene product are a frequent cause of aberrant β-catenin activation in colon and rectal cancer." (PMID 33553649, 2021). "Clinicopathologic features of 67 rectal cancer patients whose tumor/normal sample pairs were examined for APC mutations." (PMID 25025473, 2014). "Further analysis reveals that the -286 SNP mutations of CRP tend to co-occur with mutated APC particularly in rectal cancer (p = 0.04; n = 67)." (PMID 25025473, 2014). "APC mutations in the APC gene 3* of codon 1250 are associated with an increased risk for rectal cancer, and subsequently the surgical preferable choice for patients with such mutations is the restorative proctocolectomy with ileal pouch-anal anastomosis." (PMID 23737765, 2013). "Additionally, somatic mutation of APC was marginally associated with chemoradiosensitivity of rectal cancer." (PMID 36621808, 2023). "Whether the response of rectal cancer to nCRT is associated with the somatic mutations of KRAS or APC and infiltration of activated CD4+ T cells, NK cells, dendritic cells, or M2 macrophages should be verified in future investigations." (PMID 36621808, 2023). "For rectal cancer, patients with early recurrence tended to have advanced pathological N categories and TNM stage and to carry APC mutations compared with patients with late recurrence." (PMID 33919924, 2021). "The novel finding of the present study is that APC mutations were more common in CRC patients with early recurrence than in those with late recurrence, especially among those with rectal cancer." (PMID 33919924, 2021). "In another study, APC D1822V was shown to exert a protective effect in patients with colon (OR, 0.76; 95% CI, 0.60–0.97) and rectal cancer (OR, 0.73; 95% CI, 0.56–0.95), respectively." (PMID 24959234, 2014). "However, several reports suggested a difference in the expression pattern of genes in colon and rectal tumors along with the significant differences in the mutation level of APC and KRAS mutation between colon and rectal cancer." (PMID 33457124, 2020). "Three frameshift variants including two novel variants (c.907delA in APC gene and c.6743dupA in ATM) and one previously reported mutation (c.657_661delACAAA in NBN) were detected in one patient (male, Kazakh) at the age of 40 with rectum cancer." (PMID 31428572, 2019).